RNU6-454P (RNA, U6 small nuclear 454, pseudogene)
Gene: Small nuclear RNA gene on chromosome 3 (15,339,749 to 15,339,855, forward strand). Ensembl gene ENSG00000201162.
Homologues: Orthologues: chimpanzee U6 (97% identical), macaque U6 (93% identical), rabbit U6 (89% identical), dog U6 (83% identical), mouse Gm25716 (72% identical). Paralogues in human: RNU6-1094P (88% identical), RNU6-11P (88% identical), RNU6-183P (88% identical), RNU6-222P (88% identical), RNU6-37P (88% identical), RNU6-434P (88% identical), RNU6-43P (88% identical), RNU6-560P (88% identical), RNU6-939P (88% identical), RNU6-1209P (87% identical), RNU6-1329P (87% identical), RNU6-140P (87% identical), and 1287 more.